SERPINB9 (serpin family B member 9)
Description:
Granzyme B inhibitor.
Synonyms: CAP-3; CAP3; PI-9; PI9
Tractability: PROTAC: ubiquitination databases record sites on it; its protein half-life has been measured.
Gene: Protein-coding gene on chromosome 6 (2,887,169 to 2,903,309, reverse strand). Ensembl gene ENSG00000170542.
Subcellular location: Cytoplasm
Subcellular location (Human Protein Atlas): Nucleoplasm; Cytosol
Gene Ontology:
Molecular function: cysteine-type endopeptidase inhibitor activity involved in apoptotic process; protease binding; protein binding; serine-type endopeptidase inhibitor activity
Biological process: cellular response to estrogen stimulus; immune response; mast cell mediated immunity; negative regulation of apoptotic process; protection from natural killer cell mediated cytotoxicity
Cellular component: cytoplasm; cytosol; extracellular exosome; extracellular matrix; extracellular region; membrane; nucleus
Genetic constraint (gnomAD): Loss-of-function variants: 20 observed, 25.29 expected, observed/expected ratio (o/e) 0.79, 90% interval 0.56 to 1.15. The upper end of that interval is the gene's LOEUF score, 1.15, which puts it in group 5 of 6, group 1 being the genes least tolerant of losing a copy. Missense variants: 469 observed, 472.12 expected, observed/expected ratio (o/e) 0.99, 90% interval 0.92 to 1.07. Synonymous variants: 185 observed, 184.68 expected, observed/expected ratio (o/e) 1, 90% interval 0.89 to 1.13.
Homologues: Orthologues: chimpanzee SERPINB9 (99% identical), macaque SERPINB9 (83% identical), rabbit SERPINB9 (77% identical), dog SERPINB9 (74% identical), pig SERPINB9 (74% identical), rat Serpinb9 (69% identical), mouse Serpinb9 (69% identical), mouse Serpinb9b (66% identical), rat Serpinb9b (66% identical), rat Serpinb9d (65% identical), mouse Serpinb9d (64% identical), mouse Serpinb9e (63% identical), and 4 more. Paralogues in human: SERPINB6 (63% identical), SERPINB8 (62% identical), SERPINB1 (51% identical), SERPINB4 (48% identical), SERPINB10 (47% identical), SERPINB3 (47% identical), SERPINB2 (46% identical), SERPINB13 (44% identical), SERPINB11 (44% identical), SERPINB12 (41% identical), SERPINC1 (39% identical), SERPINB7 (37% identical), and 24 more.
Diseases named in the same sentence as SERPINB9 in open-access papers:
SERPINB9 is named in the same sentence as 38 diseases in open-access papers, as found by Europe PMC text mining. Sharing a sentence is not in itself a finding about the gene and the disease. The quoted sentences say what the papers report.
melanoma (8 papers, 2008 to 2023). A malignant, usually aggressive tumor composed of atypical, neoplastic melanocytes. "As such, we validated our cytotoxicity assay and documented that overexpression of SERPINB9, a natural inhibitor of granzyme B, in melanoma target cells rendered them resistant to NK-92 cytotoxicity." (PMID 36380966, 2022). "Even within a more comprehensive analysis of a correlative signature for resistance to immune checkpoint blockade in melanoma, Serpinb9 as a single element correlated with resistance." (PMID 31483286, 2019). "Multiple studies show that expression of SERPINB9 in melanomas is correlated with worse survival and poor response to immunotherapy." (PMID 26993499, 2016). "The genes BCAT1, GGH and SERPINB9 have been correlated to clinical outcome in other types of cancer, such as colorectal cancer, neuroendocrine cancer, large cell lymphoma and melanoma." (PMID 18778486, 2008). "Additionally, SERPINB9 (Serpin Family B Member 9) was recently reported to enhance resistance to ICB; SERPINB8 is a component gene of Overlap36 with unknown functions in melanoma." (PMID 36588164, 2023).
breast carcinoma (7 papers, 2014 to 2021). "Some researchers confirmed increasing concentrations of estrogen, as well as elevated expression of estrogen receptor alpha (ERα), significantly elevated SERPINB9 level in breast cancer cells, thus effectively deactivated granzyme B and mitigated NK cell-induced cell death." (PMID 33868318, 2021). "The cis-eQTL associations of 7 genes (TAPBPL, H1F0, SERPINB9, HMBOX1, MGST3, TMBIM4, THNSL2) are shared between GBM and cell lines/normal tissues; the association of 4 genes (TAPBPL, H1F0, HMBOX1, THNSL2) are common between GBM and Breast Cancer." (PMID 25133526, 2014).
colorectal cancer (4 papers, 2008 to 2022). A primary or metastatic malignant neoplasm that affects the colon or rectum. "Regarded as an endogenous inhibitor of Granzyme B, higher expression of SERPINB9 in patients with colorectal cancer was associated with superior OS." (PMID 36249755, 2022). "Moreover, both CUL2 and SOX6 are associated with colitis as well, while SERPINB9 and NINJ2 have been associated with colorectal cancer." (PMID 35371111, 2022).
lung carcinoma (3 papers, 2017 to 2025). "Here the authors perform in vivo CRISPR/Cas9 loss-of-function screens in mouse lung cancer models, revealing Serpinb9 and Adam2 as regulators of immunotherapy response." (PMID 37258521, 2023). "We overexpressed human SERPINB9 in human lung cancer cell lines A549 and H125 and evaluated cytolytic activity of ex vivo activated and expanded γδT cells derived from healthy human donors (UPN119, UPN133), termed DNT cells." (PMID 37258521, 2023). "To reveal the role of Serpinb9 in lung cancer in vivo, we genetically ablated Serpinb9 in the lung of KrasG12D;Cas9 or BrafV600E;Cas9 mice by inhaling mice with LV-CRE-sgSerpinb9-OVA at P2." (PMID 37258521, 2023).
hepatocellular carcinoma (2 papers, 2007 to 2021). A malignant tumor that arises from hepatocytes. "Increased SERPINB9 expression was also reported in patients with hepatocellular carcinoma." (PMID 34572384, 2021).
lymphoma (2 papers, 2021 to 2024). A malignant (clonal) proliferation of B- lymphocytes or T- lymphocytes which involves the lymph nodes, bone marrow and/or extranodal sites. "SERPINB9, a serine protease, protects cells from granzyme B associated apoptosis induced by cytotoxic T cells and its expression correlates with clinical outcome of several lymphomas." (PMID 33833385, 2021).
brain tumors (1 paper, 2016). "We show that brain tumors can acquire expression of SERPINB1, SERPINB4, and SERPINB9 as a potential mechanism to resist granzyme-induced cytotoxicity." (PMID 26963506, 2016).
cytomegalovirus infection (1 paper, 2021). A herpesvirus infection caused by Cytomegalovirus. "SERPINB9 could be a circulating biomarker for cytomegalovirus infection, and immunostainings confirmed the hepatocyte expression of SERPINB9 in cirrhotic hepatitis C patients." (PMID 34572384, 2021).
gastric cancer (1 paper, 2025). A primary or metastatic malignant neoplasm involving the stomach. "The qPCR validation showed that PTPRC, SERPINB9, and RAC2 had low expression in gastric cancer cells, whereas only CCL20 and BANK1 were highly expressed." (PMID 40444282, 2025).
HIV-1 infection (1 paper, 2022). The type species of lentivirus and the etiologic agent of acquired immunodeficiency syndrome (AIDS). "This compound could use three targets (ESR1, ESR2 and SERPINB9) to regulate MCM2-TUBB2A, of which MCM2 can effectively block HIV-1 infection of macrophages by inhibiting viral DNA synthesis." (PMID 36534703, 2022).
Lewis Lung Carcinoma (1 paper, 2023). "To further validate the function of Serpinb9, we genetically ablated Serpinb9 in the murine Lewis Lung Carcinoma cells (LLC1), which were established from a C57Bl/6 mouse lung tumor, harbor the activating KrasG12D mutation and form immunogenic tumors when transplanted into syngeneic mice." (PMID 37258521, 2023).
lung adenocarcinoma (1 paper, 2023). A carcinoma that arises from the lung and is characterized by the presence of malignant glandular epithelial cells. "Together, our findings unveil that depletion of Serpinb9 enhances CD8 T-cell antitumor immunity in both KrasG12D- and BrafV600E-driven mouse models of lung adenocarcinoma." (PMID 37258521, 2023).
primitive neuroectodermal tumor (1 paper, 2023). A malignant neoplasm that originates in the neuroectoderm. "In MB and in primitive neuroectodermal tumors (PNET), the granzyme inhibitors SERPINB1 and SERPINB4 were acquired in 23% and 50% of the MB, respectively, while PNETs expressed SERPINB9, SERPINB1, and SERPINB4 in 29%, 29%, and 57% of the tumors." (PMID 37509316, 2023).
seminoma (1 paper, 2024). A radiosensitive malignant germ cell tumor found in the testis (especially undescended), and extragonadal sites (anterior mediastinum and pineal gland). "This approach led us to discover the pivotal role of SERPINB9 in non-seminoma metastasis and stemness maintenance." (PMID 39528470, 2024). "Survival analysis using non-seminoma patients from TCGA TGCT dataset showed the relationship between SERPINB9 expression and worse disease-free interval (DFI)." (PMID 39528470, 2024). "Our findings highlighted the elevated expression of SERPINB9 in metastatic EC cells within non-seminoma patients." (PMID 39528470, 2024). "Given the pronounced pro-tumorigenic attributes of SERPINB9 in EC, it emerges as a compelling candidate for therapeutic targeting in non-seminoma interventions." (PMID 39528470, 2024). "The investigation of TCGA non-seminoma datasets showed enrichment of ERK1/2 cascade and canonical WNT signaling pathways in tumor samples with higher expression of SERPINB9." (PMID 39528470, 2024).
systemic lupus erythematosus (1 paper, 2024). An autoimmune multi-organ disease typically associated with vasculopathy and autoantibody production. "For example, lncRNAs, such as Hotair, LUST, anti-NOS2A, MEG9, SNHG4, TUG1, and NEAT1, have been found to be highly expressed in rheumatoid arthritis, while the expression of lnc-HSFY2–3:3 and lnc-SERPINB9–1:2 is reduced in systemic lupus erythematosus (SLE)." (PMID 38473997, 2024).
testicular seminoma (1 paper, 2026). A malignant germ cell tumor arising from the testis. "In testicular seminomas, TLSs have been associated with a more favorable prognosis, whereas non-seminomatous germ cell tumors demonstrate TLS suppression driven by SERPINB9-mediated downregulation of chemokines that promote their development." (PMID 41821902, 2026).
vitiligo (1 paper, 2022). Generalized well circumscribed patches of leukoderma that are generally distributed over symmetric body locations and is due to autoimmune destruction of melanocytes. "Additionally, previous studies have suggested significantly decreased Treg cells in vitiligo patients, suggesting that the increased SERPINB9 transcripts can lead to Treg cells apoptosis, resulting into decreased Tregs number, thereby contributing to GV pathogenesis, progression, and severity." (PMID 36157881, 2022). "Additionally, disease activity and severity-based analyses revealed significantly decreased GZMB (p = 0.019 and 0.034), SERPINB9 (p = 0.031 and p = 0.035), and ITPR1 (p = 0.0003 and p = 0.034) transcripts in active vitiligo and severe GV patients' Tregs." (PMID 36157881, 2022).
tumor (39 papers, 2011 to 2025). "For example, the expression of SERPINB9, a potential drug target and a member of the T-cell dysfunction signature genes, is upregulated in tumor cells by interferon gamma (IFNγ, encoded by the IFNG gene) in the tumor microenvironment." (PMID 37106127, 2023). "GZMB is highly expressed by cytolytic CD8+ T cells, natural killer (NK) and γδT cells to eliminate pathogenic and tumor cells and SERPINB9 is usually expressed in these cytolytic effector cells to protect them from apoptosis induced by their own GZMB57–59." (PMID 37258521, 2023). "Since type I IFNs are frequent participants in TME and most cancer cells express their receptors, induction of SERPINB9 should be a more plausible mechanism underlying the evasion of tumor cells from GrB-dependent proteolysis." (PMID 33868318, 2021). "While upregulation of SERPINB9 has been observed in several tumor types and linked with their resistance to T cell-mediated killing, a comprehensive understanding of SERPINB9 regulation in tumor cells within TME remains in the dark." (PMID 33868318, 2021). "Among the strategies that tumor cells employ to survive the adversities caused by effector lymphocytes, the one for overcoming GrB-mediated apoptosis is unique and convergent on SERPINB9, the well-defined granzyme B inhibitor that protects its host from being killed by this cytotoxic molecule." (PMID 33868318, 2021). "The presence of SerpinB9-expressing CAFs thus enhances tumor cell survival and facilitates immune evasion, contributing to a more aggressive and therapy-resistant tumor phenotype." (PMID 41439998, 2025). "To robustly validate the SERPINB9 expression at the protein level, we embarked on IHC analyses of primary tumor samples from the four patients." (PMID 39528470, 2024). "Compared with normal tissues, six proteins (GALNT6A, FOXO1, ACSM3, DNAJA1, PRDX5, and SERPINB9) were notably overexpressed in tumour tissues." (PMID 39030559, 2024). "Our research indicates that SERPINB9 plays a key role in driving tumor progression by enhancing tumor stemness and suppressing TLS." (PMID 39528470, 2024). "SERPINB9 is significantly upregulated in the C2 subtype, and previous research has demonstrated its pivotal function in enhancing tumor cell survival and promoting the existence of immune-suppressive cells within the TME." (PMID 37267125, 2023). "While ACT treatment significantly slowed the growth of control (CTRL) KrasG12D and BrafV600E tumors, loss of Serpinb9 further enhanced the effect of ACT treatment and completely blocked tumor growth in both KrasG12D;Cas9 and BrafV600E;Cas9 mice." (PMID 37258521, 2023). "Together, our in vitro and in vivo functional analyses corroborate the role of SERPINB9 as an important tumor-intrinsic mechanism in promoting resistance to immunotherapy." (PMID 37258521, 2023). "Eventually, unedited Serpinb9-wildtype escapers and other immune-editing mechanisms lead to tumor growth and death." (PMID 37258521, 2023). "Proliferation associated protein PRG3 and anti-apoptosis related protein SERPINB9 in Ca vs Liver group, and cyclin-dependent kinases CDKS up-regulated in both primary tumor and liver metastasis tissues." (PMID 36249004, 2022). "A similar molecular mechanism was demonstrated for serpinB9, an inhibitor that can directly inhibit granzyme B; tumour cells were shown to protect themselves from cytotoxic lymphocytes by up-regulating serpinB9." (PMID 33291222, 2020). "Following IR, Serpinb9-KO B16F10 tumors had a prolonged tumor growth delay equivalent to that of irradiated Ifnar1-KO B16F10 tumors." (PMID 31483286, 2019). "Tumor cells can evade GrB-mediated cell death by expression of the intracellular serine protease inhibitor SERPINB9." (PMID 21857942, 2011). "Intracellular expression of SERPINB9 by tumor cells renders them resistant to GrB-induced apoptosis." (PMID 21857942, 2011).
tumor (continued). "This intriguing concept has been well studied for SERPINB9-expressing tumor cells that efficiently inhibit GrB-induced cell death." (PMID 21857942, 2011). "As SERPINB9 protects cells from granzyme B induced apoptosis, its reduced functionality in macrophage-like cells, which are primarily found in the tumor core, can lead to increased apoptosis and hence a reduced immune response." (PMID 39936571, 2025). "Additionally, our study identified the role of SERPINB9 in suppression of tertiary lymphoid structure (TLS)-associated cytokines and promoting tumor progression." (PMID 39528470, 2024). "SERPINB9 is a known inhibitor of granzyme and may mediate tumor immune evasion by apoptosis inhibition." (PMID 30854481, 2019). "Interestingly, this cluster also has an elevated expression of MYH3, an embryonic form of myosin heavy chain, several cardiac cytoskeletal genes (ACTC1, TNNT2), and SERPINB9, which has previously been shown to protect tumor cells from granzyme B secreted by cytotoxic T lymphocytes." (PMID 41373578, 2025). "Moreover, fluorescent IHC (F-IHC) analyses revealed a diminished intensity of staining for the stemness-related marker OCT4, alongside an intensified staining for markers indicative of differentiation (AFP, ACTA2 and CD57) in xenograft tumor tissues following SERPINB9 knockdown." (PMID 39528470, 2024). "Thus, inhibition of Serpinb9 and other pro-tumor elements downstream of IFN-I in tumor cells may enhance the efficacy of radiotherapy and immunotherapy." (PMID 36755342, 2023). "The expression of TAPBPL, SERPINB9, RCAN1, TMBIM4, JUNB, IL4R, and LY75 is significantly up-regulated in tumor samples with their high expression associated with a poor outcome; the expression of MGST3 is down-regulated in tumor samples with its low expression associated with poor prognosis." (PMID 25133526, 2014). "In this study, we compared tumor-infiltrating CD3+, CD4+, CD8+ T-cells, and granzyme inhibitors (SERPINB1, SERPINB4, and SERPINB9) between HPV-positive and HPV-negative tumors and the relation with survival." (PMID 26993499, 2016). "Notably, we discovered that the expression of SERPINB9 in EC contributed to the suppression of TLS, thereby fostering a tumor-promoting microenvironment." (PMID 39528470, 2024). "Upon SERPINB9 knockdown, the NCCIT cells exhibited a marked reduction in tumor growth." (PMID 39528470, 2024). "Tumor cells have evolved many mechanisms to resist CTL- and NK-mediated killing, including the expression of the serine protease inhibitor serpinB9/proteinase inhibitor 9 (PI-9)." (PMID 37894728, 2023). "Since Serpinb9 was not essential for tumor growth in B16F10 cells, we used these tumors to examine the effect of IR." (PMID 31483286, 2019). "Tumor cells can escape from cytotoxic lymphocyte-induced killing by expression of cell death inhibitors in their cytoplasm, like the caspase-inhibitors XIAP and FLIP, and the GrB-inhibitor SERPINB9 (PI9)." (PMID 21857942, 2011). "However, activation of IFNAR1 in tumor cells by type I IFN may help them resist T lymphocytes and NK cells killing after radiation by upregulating Serpinb9, which inhibits the cytotoxic molecule granzyme B secreted by T and NK cells." (PMID 36755342, 2023). "Serpinb9 restoration did not affect Ifnar1-KO MC38 or B16F10 tumor growth without treatment." (PMID 31483286, 2019). "Whether SERPINB9 might play a role in tumor recurrence is not known." (PMID 31483286, 2019).